CT45A8 (cancer/testis antigen family 45 member A8)
Tractability: PROTAC: ubiquitination databases record sites on it.
Gene: Protein-coding gene on chromosome X (135,846,497 to 135,854,538, reverse strand). Ensembl gene ENSG00000278085.
Subcellular location (Human Protein Atlas): Nucleoli; Nucleoplasm
Homologues: Orthologues: rat Ct45a9 (29% identical), mouse Ct45a (27% identical), Caenorhabditis elegans ints-6 (17% identical), Drosophila melanogaster IntS6 (16% identical). Paralogues in human: CT45A2 (100% identical), CT45A9 (100% identical), CT45A3 (98% identical), CT45A1 (98% identical), CT45A5 (98% identical), CT45A6 (98% identical), CT45A7 (98% identical), CT45A10 (95% identical), SAGE1 (35% identical), INTS6L (32% identical), INTS6 (26% identical).